C1QC (complement C1q C chain)
Description:
Core component of the complement C1 complex, a multiprotein complex that initiates the classical pathway of the complement system, a cascade of proteins that leads to phagocytosis and breakdown of pathogens and signaling that strengthens the adaptive immune system. The classical complement pathway is initiated by the C1Q subcomplex of the C1 complex, which specifically binds IgG or IgM immunoglobulins complexed with antigens, forming antigen-antibody complexes on the surface of pathogens: C1QA, together with C1QB and C1QC, specifically recognizes and binds the Fc regions of IgG or IgM via its C1q domain. Immunoglobulin-binding activates the proenzyme C1R, which cleaves C1S, initiating the proteolytic cascade of the complement system. The C1Q subcomplex is activated by a hexamer of IgG complexed with antigens, while it is activated by a pentameric IgM. The C1Q subcomplex also recognizes and binds phosphatidylserine exposed on the surface of cells undergoing programmed cell death, possibly promoting activation of the complement system.
Synonyms: C1QG; C1Q-C; C1QD3
Tractability: Small molecule: a structure with a bound ligand is known. Antibody: UniProt places it where antibodies can reach, with high confidence; its Gene Ontology location is reachable by antibodies, with high confidence; UniProt predicts a signal peptide or a membrane-spanning region.
Gene: Protein-coding gene on chromosome 1 (22,642,558 to 22,648,110, forward strand). Ensembl gene ENSG00000159189.
Subcellular location: Secreted; Cell surface
Pathways (Reactome):
Immune System: Classical antibody-mediated complement activation; Initial triggering of complement; Regulation of Complement cascade
Gene Ontology:
Molecular function: IgG binding; IgM binding; phosphatidylserine binding; protein binding
Biological process: complement activation, classical pathway; negative regulation of granulocyte differentiation; negative regulation of macrophage differentiation; immune response; synapse pruning
Cellular component: blood microparticle; cell surface; complement component C1 complex; complement component C1q complex; extracellular matrix; extracellular region; symbiont cell surface; postsynapse; synapse; extrinsic component of postsynaptic membrane; extrinsic component of presynaptic membrane; glutamatergic synapse
Genetic constraint (gnomAD): Loss-of-function variants: 5 observed, 6.08 expected, observed/expected ratio (o/e) 0.82, 90% interval 0.43 to 1.64. That is too few expected variants to judge how well the gene tolerates losing a copy. Missense variants: 299 observed, 315.47 expected, observed/expected ratio (o/e) 0.95, 90% interval 0.86 to 1.04. Synonymous variants: 166 observed, 148.87 expected, observed/expected ratio (o/e) 1.12, 90% interval 0.98 to 1.27.
Homologues: Orthologues: chimpanzee C1QC (99% identical), macaque C1QC (96% identical), pig C1QC (76% identical), rat C1qc (76% identical), guinea pig C1QC (75% identical), mouse C1qc (74% identical), dog C1QC (72% identical), rabbit C1QC (67% identical), tropical clawed frog C1QC (46% identical), zebrafish c1qc (45% identical). Paralogues in human: C1QB (51% identical), C1QA (38% identical), C1QTNF9 (38% identical), COL8A1 (37% identical), C1QTNF9B (37% identical), C1QTNF5 (36% identical), ADIPOQ (36% identical), COL10A1 (36% identical), COL8A2 (36% identical), C1QTNF7 (36% identical), C1QTNF2 (35% identical), OTOL1 (33% identical), and 11 more.
Diseases named in the same sentence as C1QC in open-access papers:
C1QC is named in the same sentence as 88 diseases in open-access papers, as found by Europe PMC text mining. Sharing a sentence is not in itself a finding about the gene and the disease. The quoted sentences say what the papers report.
COVID-19 (10 papers, 2020 to 2024). A disease caused by infection with severe acute respiratory syndrome coronavirus 2. "In the COVID-19 group, coagulation factor XIII A chain (F13A1) and contactin associated protein 2 (CNTNAP2) exhibited the strongest upregulation, with CD14, C1QC, cytochrome C oxidase subunit 7C (COX7C) and (APOE) being increased in the AD group." (PMID 36211330, 2022). "Similarly, in previous reports, FGB, FGG, complements C4, C3, C5, C2, C9, and complement C1q subcomponent subunits A, B, and C (C1QA, C1QB and C1QC) were found to be upregulated in the lung tissues of patient with COVID-19." (PMID 38882332, 2024). "Specifically, signatures of plasma cells (IGHG3, IGKC, IGHM, JCHAIN, IGHG2, IGKV4-1, IGLV3-1, IGHA1), activated fibroblasts (COL1A1, COL1A2, COL3A1), inflammatory cytokines (CXCL9, CCL18) and complement factors (C1QB, C1QC) dominated the DE genes for the COVID-19 lung sections." (PMID 37858234, 2023). "Clusters A to C contain proteins with lower levels in COVID-19 convalescents, e.g. proteins functioning in cell adhesion and platelet degranulation (e.g. fibrinogen A (FGA), VWF), and innate immunity/the complement system (e.g. C1R, C1S, C1QA, C1QC, and GGH)." (PMID 38396092, 2024).
glioma (7 papers, 2019 to 2024). A benign or malignant brain and spinal cord tumor that arises from glial cells (astrocytes, oligodendrocytes, ependymal cells). "As a result of C activation, high expression of C1QA, C1QB, and C1QC, encoding the three chains of C1q, were observed in gliomas." (PMID 37174113, 2023). "We, therefore, performed a bioinformatics analysis, using Oncomine dataset and UALCAN database in order to assess whether the expression of the genes encoding for the three chains of C1q (C1qA, C1qB, and C1qC) could serve as a potential prognostic marker for gliomas." (PMID 31649675, 2019). "Previous studies have shown that C1q, the first recognition subcomponent of the complement classical pathway, comprises three chains (C1qA, C1qB, and C1qC) and exerts complex effects on tumorigenesis of multiple tumors, including prostate, and ovarian cancer as well as gliomas." (PMID 33014868, 2020). "C1qA, C1qB, and C1qC expression in gliomas in the datasets used in the current study with Oncomine." (PMID 31649675, 2019). "Through high-throughput expression profiling, WGCNA, lasso, and multivariate Cox analysis, we acquired eight genes (HCK, HAVCR2, CD37, LPAR5, NAGA, C1QC, FCER1G and AIF1) to construct the MRGs signature in Grade II/III glioma patients." (PMID 33186124, 2020).
colon cancer (6 papers, 2021 to 2024). "We also screened out the differentially expressed gene C1QC, which regulates the infiltration of macrophages in colon cancer and affects the prognosis of colon cancer patients." (PMID 35765947, 2022). "Therefore, it is speculated that the expression levels of C1QA, C1QB, and C1QC are closely related to the development of colon cancer." (PMID 35765947, 2022). "In colon cancer patients, two main populations of TAMs with distinct functional features have been identified by transcriptomic analyses: Secreted phosphoprotein 1 (SPP1) positive TAMs and complement C1q C chain (C1QC) positive TAMs." (PMID 36189323, 2022). "Besides, the C1QC+ TAMs and SPP1+ TAMs could not be explained by the expression analyses based on genes associated with M1 and M2 TAMs in the colon cancer." (PMID 34295336, 2021).
osteosarcoma (5 papers, 2021 to 2024). A usually aggressive malignant bone-forming mesenchymal neoplasm, predominantly affecting adolescents and young adults. "The differential expressions of C1QA, C1QB and C1QC were found to be closely related to the survival prognosis, pathological features, and tumor microenvironment of osteosarcoma, which can help improve the clinical prognosis and immunotherapy." (PMID 35765947, 2022). "In a recent analysis, complement classical pathway genes C1QA, C1QB, C1QC were proved to be protective factors for survival in osteosarcoma." (PMID 35493104, 2022). "However, the immunomodulatory mechanism and actions of C1qA, C1qB and C1qC in osteosarcoma are not clear." (PMID 34079754, 2021).
breast carcinoma (4 papers, 2021 to 2025). "Bandini also confirmed that C1qA, C1qB and C1qC expression levels were positively linked to a good prognosis in breast cancer patients using in vivo investigation of C1q-deficient mice." (PMID 34079754, 2021). "In contrast to the complex phenotypes of tumor-associated macrophages (TAMs) in the breast cancer and lung cancer TMEs, the TAMs in HCC exhibited remarkable dichotomy (VCAN+ TAMs and C1QC+ TAMs)." (PMID 37383234, 2023). "In contrast to the dynamic spectrum of TAM phenotypes in lung and breast cancer, we identified that TAMs in HCC consisted of VCAN+ and C1QC+ TAMs, exhibiting remarkable dichotomy." (PMID 37383234, 2023). "TUBA1B+ TAMs, C1QC+ TAMs and VCAN+ TAMs were more prevalent in HER2+ breast cancer, whereas IL1B+ TAMs, SLC40A1+ TAMs and APOC1+ TAMs were more dominant in ER+ breast cancer, which illustrates the heterogeneity of TAM subtypes in various molecular subtypes of breast cancer." (PMID 39232806, 2024).
Insulin resistance (4 papers, 2021 to 2024). Increased resistance towards insulin, that is, diminished effectiveness of insulin in reducing blood glucose levels. "One bioinformatics study found C1QC to be a potential hub gene, which is associated with immune cell infiltration related with the progression of obesity-related diabetes or insulin resistance, respectively." (PMID 35634436, 2022). "C1QC is a C1q/TNF-related protein that is reportedly associated with adipose tissue dysfunction and the infiltration of immune cells, especially macrophages, which may contribute to insulin resistance and the development of diabetes." (PMID 39526504, 2024). "This article revealed that CSF1R, C1QC, and TYROBP were potential hub genes associated with immune cells' infiltration and the function of proinflammation, especially adipose tissue macrophages, in the progression of obesity-induced diabetes or insulin-resistance." (PMID 33564304, 2021).
melanoma (4 papers, 2020 to 2023). A malignant, usually aggressive tumor composed of atypical, neoplastic melanocytes. "TREM2+ TAMs from ESCC exhibited a consistent expression pattern and identical signature genes (TREM2, SPP1, APOE, C1QC, C1QB, and C1QA) with melanoma cells, suggesting that TREM2+ TAMs were associated with immunotherapy resistance in ESCC." (PMID 37187751, 2023). "Our findings will help reveal the multifaceted roles of C1QA, C1QB, and C1QC and provide evidence for future immunotherapy of melanoma." (PMID 36110204, 2022). "C1QC encodes the C‐chain polypeptide of Complement C1q, widely expressed in the TME among various types of human malignancies, suggesting that C1QC could also be a significant factor in melanoma." (PMID 33169786, 2020). "We focused on macrophages and identified TREM2+ TAMs specifically expressing TREM2, SPP1, APOE, C1QC, C1QB, and C1QA, which were significantly upregulated in melanomas not responsive to ICB therapy." (PMID 37187751, 2023).
Sepsis (4 papers, 2023 to 2025). Sepsis is defined as life-threatening organ dysfunction caused by a dysregulated host response to infection. "A large number of patients surviving sepsis exhibit mental and cognitive impairment, and C1q pathways (C1qb, C1qc, and Tyrobp) are associated with the mental and cognitive impairment observed in the post-sepsis syndrome." (PMID 40426888, 2025). "Among the top 40 DEGs analyzed by RNA sequencing of whole hippocampus tissue at day 3 following sepsis induction, we observed up-regulation of C1qa, C1qb, and C1qc encoding for complement factor C1q." (PMID 37235660, 2023). "At the same time, we also detected the C1q signaling pathway and found that the expression of C1QC was elevated in the peripheral blood of patients with sepsis, while C1QA had no significant change." (PMID 36845133, 2023).
tuberculosis (4 papers, 2014 to 2021). A chronic, recurrent infection caused by the bacterium Mycobacterium tuberculosis. "Both C1q gene expression on mononuclear cells in peripheral blood and the serum C1q protein levels are related to active disease in human tuberculosis, and there is a progressive decrease in plasma C1q mRNA expression and plasma C1qC protein during anti-tuberculosis chemotherapy." (PMID 34790186, 2021). "Recently, increased circulating C1q and C1qC gene expression in patients with active tuberculosis compared to healthy controls and individuals with latent TB infection has been reported indicating its potential use as a biomarker to discriminate active TB from latent TB cases." (PMID 29499046, 2018). "Finally, C1qC protein level was quantified in the pleural fluid of tuberculosis and non-tuberculosis pleurisy." (PMID 24647646, 2014). "Additionally, C1qC protein level in pleural effusion shows improved power in discriminating tuberculosis from non-tuberculosis pleurisy when compared to other inflammatory markers, such as IL-6 and TNF-α." (PMID 24647646, 2014).
atherosclerosis (3 papers, 2020 to 2022). A disease characterized by the build-up of fatty material and calcium deposition in the arterial wall resulting in partial or complete occlusion of the arterial lumen. "In this study, we suggested that the progression of atherosclerosis might be related to CD86, C1QB, CD53, C1QC, NCF2, and ITGAM and that it plays a role in regulating immune-competent cells such as T cell CD8 and macrophages M0 and M2." (PMID 32821283, 2020).
Immunodeficiency (3 papers, 2019 to 2021). Failure of the immune system to protect the body adequately from infection, due to the absence or insufficiency of some component process or substance. "Homozygous nonsense mutation in the C1QC (Complement C1q C Chain) gene was also among identified genes which explains the immunodeficiency and severe SLE phenotype of that patient." (PMID 34362117, 2021). "We identified one previously reported homozygous nonsense mutation in the C1QC (Complement C1q C Chain) gene, which explains the immunodeficiency and severe SLE phenotype of that patient." (PMID 30707351, 2019).
malaria (3 papers, 2016 to 2025). Malaria is a serious and sometimes fatal disease caused by a parasite that commonly infects a certain type of mosquito which feeds on humans. "The gene Cfp displayed a very similar expression pattern as C1qa, C1qb, and C1qc in response to blood-stage malaria, with a faster increase towards day 4 p.i. after an initial faster decrease on day 1 p.i. in vaccinated mice than in unvaccinated mice." (PMID 40243929, 2025). "Differentially expressed probes form these canonical pathways that were previously shown to play a role in severe malaria pathogenesis were TLR2, TLR4, TLR8, HSPA6, CR1, C1qA, C1qB, C1qC, FOS, and GZMB." (PMID 26961973, 2016). "Notably, complement genes (C1QA, C1QB, C1QC), apoptotic genes (PDL1, PDL2, APOL1, APOL2, FAS), inflammatory caspases (CASP1, CASP5), TLR pathway genes (TLR1, TLR4, TLR5, TLR8), cytokines (IL6, IL10), and granzyme (GZMB) were among the genes upregulated during symptomatic malaria." (PMID 39161730, 2024).
Obesity (3 papers, 2021 to 2024). Accumulation of substantial excess body fat. "Two hub genes (CCL18 and C1QC) associated with both obesity and DN were ultimately identified by constructing a PPI network." (PMID 39526504, 2024). "Through comprehensive bioinformatics analyzing and experimental verification, our study found that three hub genes CSF1R, C1QC, and TYROBP were associated with immune cells infiltration, especially macrophages in adipose tissue under obesity induced IR condition." (PMID 33564304, 2021). "Two hub genes (CCL18 and C1QC) were ultimately identified by constructing a PPI network; these genes may both be involved in the development of type 2 DN and obesity." (PMID 39526504, 2024).
prion disease (3 papers, 2019 to 2021). A transmissible disease that is caused by a protein that is able to induce abnormal folding of normal cellular proteins, leading to characteristic spongiform brain changes, which are associated with neuronal loss without an inflammatory response. "The genes C1QB, C1QC, C7, and NCAM1 were downregulated for Ca and partake in the prion disease pathway." (PMID 31481722, 2019).
staphylococcus aureus infection (3 papers, 2019 to 2023). An infectious process in which the bacteria Staphylococcus aureus is present. "The genes C1QA, C1QB, C1QC, C1S, C3, and C4A in cluster 2 were predominantly enriched in top ten pathways including Staphylococcus aureus infection, pertussis and complement and coagulation cascades." (PMID 37409113, 2023).
Stroke (3 papers, 2019 to 2025). Sudden impairment of blood flow to a part of the brain due to occlusion or rupture of an artery to the brain. "The classical pathway, initiated by C1q‐a protein composed of C1QA, C1QB, and C1QC subunits, is a major contributor to stroke‐induced inflammation and vascular injury." (PMID 40842166, 2025). "At 8 weeks post-stroke, the top 10 genes were Cd44 (degree = 14), Fcgr2b (degree = 13), C1qb (degree = 13), Cd74 (degree = 12), C1qc (degree = 11), Cd14 (degree = 10), C4a (degree = 10), Spp1 (degree = 10), RT1-A2 (degree = 9), and Itgb2 (degree = 9)." (PMID 31888302, 2019).
cervical cancer (2 papers, 2021 to 2022). A primary or metastatic malignant neoplasm involving the cervix. "In terms of C1q-related molecules, C1QC+ tumor-associated macrophages can predict the prognosis, tumor stage, and immune cell infiltration of patients with cervical cancer, which helps treat cervical cancer." (PMID 35765947, 2022). "We speculate that if C1QC+ TAMs and SPP1+ TAMs gene signatures can divide TAMs of cervical cancer patients into two distinct functional subsets, patients with different levels of C1QC+ TAMs and SPP1+ TAMs gene signatures may have different clinical features." (PMID 34295336, 2021). "However, whether TAMs in cervical cancer show as the M1 and M2 phenotypes or C1QC+ and SPP1+ TAMs phenotypes remains unknown." (PMID 34295336, 2021). "It is important to determine the role of C1QC+ and SPP1+ TAMs subsets in cervical cancer evolution and progression, and some ongoing experiments are in process." (PMID 34295336, 2021). "C1QC+ and SPP1+ TAMs gene signatures were obtained from TAMs; however, they could significantly divide patients into subgroups with distinct clinical outcomes, implying the importance of TAMs in the development of cervical cancer." (PMID 34295336, 2021).
cutaneous melanoma (2 papers, 2022 to 2023). A primary melanoma arising from atypical melanocytes in the skin. "However, the effect of C1QA, C1QB, and C1QC expression on tumour immunity and prognosis of cutaneous melanoma remains unclear." (PMID 36110204, 2022). "However, C1QC overexpression reported a better skin cutaneous melanoma prognosis, not consistent with the promotive role of C1QC in cancer progression as mentioned in existing research." (PMID 36992705, 2023).
glomerulonephritis (2 papers, 2020 to 2022). A renal disorder characterized by damage in the glomeruli. "C1QC encodes the C-chain polypeptide of serum complement subcomponent C1q, a deficiency of which is associated with lupus erythematosus and glomerulonephritis." (PMID 35773742, 2022). "C1QB (complement C1q B chain) or C1QC (complement C1q C chain) encodes the C-chain or B-chain polypeptide of serum complement subcomponent C1q, respectively, and deficiency of C1q is associated with glomerulonephritis and lupus erythematosus." (PMID 32821283, 2020).
pancreatic cancer (2 papers, 2023 to 2025). "We visualized changes by UMAP, and found that C1qa, C1qb, and C1qc, immunosuppressive macrophage markers in pancreatic cancer, were upregulated in the ON compared with the OFF group." (PMID 39782689, 2025). "The macrophage 1 population was defined by Apoe, C1qa, and C1qc markers of TAMs in mouse and human pancreatic cancer, while the macrophage 5 population expressed Ear2 and Retnla." (PMID 36727849, 2023).